CDX2 (caudal type homeobox 2)
Diseases named in the same sentence as CDX2 in open-access papers (continued):
Sharing a sentence is not in itself a finding about the gene and the disease.
colorectal adenocarcinoma (45 papers, 2007 to 2026). The most common type of colorectal carcinoma. "Virtually all colorectal adenocarcinomas are positive for CDX2, with relative loss of expression in microsatellite unstable subtype." (PMID 33504059, 2021). "Recent studies suggest CDX2 expression may also serve as a clinicopathological associations in colorectal adenocarcinoma." (PMID 41388313, 2025). "CDX2 is closely associated with the development of colorectal adenocarcinoma." (PMID 40636692, 2025). "Therefore, we did this study to classify colorectal adenocarcinomas into high and low expression groups using a semi-quantitative scoring system and to evaluate the association of CDX2 expression with histological differentiation and tumor progression." (PMID 41388313, 2025). "CDX2 is a transcription factor, a useful marker of intestinal NENs and, because of its association with GI differentiation, it is also found in gastrin-positive pancreatic NENs and colorectal adenocarcinoma." (PMID 37685605, 2023). "In addition loss of cdx-2 immunoreactivity was implicated as diagnostic feature in poorly differentiated colorectal adenocarcinoma." (PMID 22824143, 2012). "CDX2, an intestine-specific transcription factor, is essential for colorectal epithelial differentiation and has been widely studied as a biomarker in colorectal adenocarcinoma (CRC)." (PMID 41388313, 2025). "In general, small intestinal adenocarcinomas, as in our case, have diffuse positivity for CK7 and lower CK20 and CDX2 expression rates than large intestine adenocarcinomas." (PMID 40182334, 2025). "Histopathological examination revealed glandular structures resembling colorectal adenocarcinoma, with immunohistochemical positivity for CDX2, CK20, and SATB2, and negativity for TTF-1 and CK7." (PMID 41561768, 2025). "CDX2 positivity was initially thought to be specific to colorectal adenocarcinoma, but more recent evidence has indicated its expression in bladder cancer." (PMID 40430111, 2025). "CDX2 is a marker shown to be expressed in well-differentiated NETs of intestinal origin; however, it can also be seen in colorectal adenocarcinoma." (PMID 39176372, 2024). "CDX2 is highly expressed in various gastrointestinal cancers, such as colorectal adenocarcinomas (70–85%), gastroesophageal (50%), stomach (55–70%), ampulla (65–80%) and small intestine tumors (60%)." (PMID 37200263, 2023). "CDX2 marks 86–100% well- and moderately-differentiated colorectal adenocarcinomas but is also immune-positive in intestinal metaplasia, wherever it occurs." (PMID 37174934, 2023). "The diffuse and intense immunohistochemical expression of CDX2 is useful in distinguishing colorectal adenocarcinoma from other sites." (PMID 37200263, 2023). "Taken together, these data show that THRA promoter activity is positively regulated by the Wnt/β‐catenin pathway and CDX2 in human colorectal adenocarcinoma cell lines." (PMID 36217307, 2022). "CDX2 is preferentially expressed in the intestinal epithelium, thus is very sensitive for detecting colorectal adenocarcinoma, but there have been reported cases of primary lung adenocarcinomas that express CDX2." (PMID 35027072, 2022). "A homeobox protein, CDX2, also known as a representative regulator of intestinal differentiation is a sensitive and specific marker of colorectal adenocarcinoma." (PMID 32867793, 2020). "Generally, CK20+, CK7-, and CDX-2+ statuses are considered to be markers of colorectal adenocarcinoma." (PMID 28969003, 2017). "Morphologically, PEAC has histological and immunohistochemical similarities to colorectal adenocarcinoma, while some PEACs are positive for immunohistochemical markers of enteric differentiation, such as CDX-2 and CK20/7." (PMID 28969003, 2017). "The CK7-/CK20+ phenotype showed a specificity of 96.7% in predicting colorectal adenocarcinomas, which was superior to that of CDX2 expression." (PMID 22268990, 2012).
colorectal adenocarcinoma (continued). "First, the histological architecture inherent to colorectal adenocarcinoma, primarily the ability to form dysplastic glands as well as the presence of CDX-2 positive nuclei is maintained in the PDCCEs throughout multiple passages (>10)." (PMID 22675560, 2012). "The CK7-/CK20+/CDX2+ phenotype was highest, accounting for 63% (74/118) of colorectal adenocarcinomas." (PMID 22268990, 2012). "The CK7-/CK20+ immunophenotype is more specific in differentiating colorectal adenocarcinomas from pancreatic and gastric adenocarcinomas than CDX2 expression." (PMID 22268990, 2012). "Among colorectal adenocarcinomas, the relationship between tumor grade and CDX2 staining has been controversial." (PMID 22268990, 2012). "Determining the CK7/CK20 phenotype proved to be more specific in differentiating colorectal adenocarcinoma from pancreatic and gastric adenocarcinomas (specificity 96.7%) than the expression of CDX2 was." (PMID 22268990, 2012). "The clinical utility of CDX2 was confirmed to be fairly specific for the identification of adenocarcinoma of the gastrointestinal tract, particularly colorectal adenocarcinoma, in the primary and metastatic setting." (PMID 22074191, 2011). "Immunohistochemistry has demonstrated 60% to 98% CDX2 expression in primary and secondary colorectal adenocarcinomas." (PMID 21689464, 2011). "MC is known to be associated with MSI-H, and some studies examining the immunohistochemical characteristics of this tumor have shown that it can be differentiated from poorly differentiated colorectal adenocarcinoma by a loss of MLH-1 staining and the intestinal transcription factor CDX2." (PMID 31845183, 2020). "The authors suggested that CdX2 was more specific than CK 20 for colorectal adenocarcinoma and that inclusion of CdX2 in antibody panels to distinguish between primary and secondary epithelial colorectal malignancies may be helpful." (PMID 28913087, 2016). "However, among colorectal adenocarcinomas, the relationship between tumor grade and CDX2 staining has been controversial." (PMID 25299496, 2014). "CDX2 and mCEA are rarely expressed in CRSmCC and hence they may be of value in differentiating it from poorly differentiated colorectal adenocarcinoma." (PMID 17803816, 2007). "Typically, primary colorectal adenocarcinomas are CK7-negative and strongly express CK20, CDX2, and SATB2.15,16) In our case, the intestinal tumors were negative for CK7 and CK20, with absent to weak CDX2 expression, and only weak SATB2 staining." (PMID 41159019, 2025). "The rectal cancer markers CK20 (+), CDX-2 (+), and SATB2 (+) are classic colorectal adenocarcinoma phenotypes, while CK7 (-), TTF-1 (-), and NapsinA (-) can exclude lung metastasis." (PMID 40837582, 2025). "In another study, Raspollini proved that immunostaining with antibodies anti-CDX-2, CK7, CK20, and CEA can be used to differentiate a primary bladder adenocarcinoma from a secondary colorectal adenocarcinoma." (PMID 39070414, 2024). "Meanwhile, caudal type homeobox 2 (CDX-2) is only expressed by intestine cells in adults and can be also employed to determine the colorectal adenocarcinoma." (PMID 37483522, 2023). "The results were CDX2(+), CK7(−), CK20(partial+) and VILLIN(partial+), which supported the phenotype of primary colorectal adenocarcinoma." (PMID 34162944, 2021). "Previous data of CDX2 ChIP-seq tracks from both LS174T cells and Caco-2 cells, human colorectal adenocarcinoma-derived cell lines which have been used as a model for intestinal epithelium, were analyzed." (PMID 30087389, 2018). "In the present study, we compared the sensitivity and specificity of CDX2 expression and the CK7-/CK20+ phenotype in differentiating colorectal adenocarcinomas from pancreatic and gastric adenocarcinomas." (PMID 22268990, 2012). "CDX2 immunostaining, which is commonly observed in colorectal adenocarcinoma, was negative in the present patient." (PMID 40491286, 2026).
colorectal adenocarcinoma (continued). "Colorectal adenocarcinoma is typically CDX-2 positive, cytokeratin (CK) 20 positive, and CK 7 negative." (PMID 40430111, 2025). "CDX2, CK7, CK20, and SATB2 were expressed in colorectal adenocarcinoma." (PMID 37608278, 2023). "The immune markers CK20, CDX2 and Villi protein (Villin) are positively expressed in colorectal adenocarcinoma with absence of thyroglobulin and calcitonin." (PMID 37032350, 2023). "Hematoxylin and eosin (H&E) staining and immunohistochemistry (IHC) analyzes showed that our CCOs mimicked the tissue architecture of their original cancers and retained the expression of colorectal adenocarcinoma markers cytokeratin 20 (CK20) and caudal-type homeobox 2 (CDX2)." (PMID 35990917, 2022). "Histologically, they appear indistinguishable from other colorectal adenocarcinomas, with variable immunohistochemical reactivity for CDX2, CK20, and CK7." (PMID 36291953, 2022). "Moreover, H&E and anti-CDX2, CK7, CK20 and VILLIN IHC staining of xenografts also confirmed its colorectal adenocarcinoma characteristics." (PMID 34162944, 2021). "The new WHO book classifies anal adenocarcinomas as primary if arising from mucosal glandular epithelium, which shares the same immunoprofile as colorectal adenocarcinoma (CK7+/−, CK20+/CDX2+), or from anal glands, which shares the same immunoprofile as skin adnexal carcinoma (CK7+/CK20−/CDX2-)." (PMID 32209119, 2020). "In addition, we found that three (CDX1, CDX2, and KLF4) of the four transcription genes (CDX2, KLF4, CDX1, and ELF3) with low expression in CSCC also showed low expression in colorectal adenocarcinoma, while ELF3 achieved the opposite result in colorectal adenocarcinoma." (PMID 35194959, 2022). "The immunostaining profile of our patient (strongly positive CK7 and positive TTF-1 with negative CDX2/CK20) supported that her rectosigmoid tumor causing near-total rectal occlusion was metastatic adenocarcinoma of lung origin, rather than primary colorectal adenocarcinoma." (PMID 30961608, 2019). "E.The most common immunophenotype for colorectal adenocarcinoma is positive CK7 and CDX2 and negative CK20." (PMID 39403181, 2024). "E.The most common immunologic staining pattern for colorectal adenocarcinoma is positive CK7 and CDX2 and negative CK20 – Incorrect." (PMID 39403181, 2024). "This IHC staining profile (strongly positive CK7 and positive TTF-1/Napsin-A with negative CDX2/CK20) supported metastatic adenocarcinoma of lung origin, rather than primary colorectal adenocarcinoma." (PMID 30961608, 2019). "We also evaluated the sensitivity, specificity, positive predictive value, and negative predictive value of CDX2 expression and CK7-/CK20+ immunophenotype to differentiate colorectal adenocarcinoma from pancreatic and gastric adenocarcinomas." (PMID 22268990, 2012). "Sensitivity, specificity, and positive/negative predictive values of CDX2 expression and CK7-/CK20+ immunophenotype in differentiating colorectal adenocarcinomas from pancreatic and gastric adenocarcinomas." (PMID 22268990, 2012). "We also evaluated the sensitivity, specificity, positive predictive value, and negative predictive value of CDX2 expression and CK7-/CK20+ immunophenotype to differentiate colorectal adenocarcinomas from pancreatic and gastric adenocarcinomas." (PMID 22268990, 2012). "The combination of CK7+/CDX-2+ was reported to have a high sensitivity (71.3%) and specificity (82%) in differential diagnosis of PEAC from colorectal adenocarcinoma, while combining cadherin-17 (negative) and SATB homeobox 2 (negative) also showed high sensitivity (77.0%) and specificity (100%)." (PMID 35172862, 2022).
lung carcinoma (31 papers, 2007 to 2026). "The studies showcased different gene polymorphisms to be associated with an increased risk of lung cancer: TaqI, ApaI, BsmI, FokI, and Cdx2." (PMID 38928369, 2024). "According to a meta-analysis, polymorphisms in Bsm1, Cdx2, and Taq1 increase the risk of developing lung cancer." (PMID 39335182, 2024). "Genetic variations in the VDR gene, particularly the polymorphisms Taql, Apal, Bsml, Fokl, and Cdx2, have been associated with an increased risk of lung cancer." (PMID 38928369, 2024). "However, the presence of specific Cdx2 and Bsm1 variants was associated with a lower risk of lung cancer, while Taq1 was associated with an increased risk of this cancer." (PMID 39335182, 2024). "Mucinous AC is the diagnostically most challenging group of primary lung cancers, and mainly data on CDX2 and CK20 is found in the literature, with 0–10% and 31–60% positive cases, respectively, in studies reporting both markers." (PMID 37349623, 2024). "As a tumor suppressor, CDX2 prevents lung cancer proliferation by suppressing the Wnt signaling pathway." (PMID 37901797, 2023). "ELMO3, in coordination with CDX2 plays a role in cellular migration in the intestine and during metastasis in lung cancer." (PMID 34178034, 2021). "In lung cancer cells, restored CDX2 expression suppressed cell proliferation by arresting the cell G1/S transition." (PMID 30631044, 2019). "Interestingly, CDX2 was found to inhibit Wnt signaling in lung cancer cells via suppression of c-MYC, cyclin D1 and survivin expression." (PMID 40002854, 2025). "In addition, both VDR (Fok1: rs2228570) and VDR (Cdx-2: rs11568820) displayed a protective role in lung cancer development in the heterozygous and dominant models." (PMID 38482381, 2024). "Consequently, Cdx-2, Bsm1 Taq1, and Fok1, which are VDR polymorphisms, were found to be the alterations with the highest correlations with lung cancer development." (PMID 38928369, 2024). "For example, immunohistochemical profiling (TTF-1+/NapsinA+ in lung cancer, CK20-/CDX-2- in ovarian cancer) and site-specific pathological features were critical for confirming the independence of the four tumors." (PMID 41584613, 2025). "The most useful immunohistochemical stains to differentiate gastrointestinal carcinoma from lung carcinoma are TTF-1, cytokeratin 7, cytokeratin 20, CDX2, and villin." (PMID 23119210, 2012). "Small bowel metastases from primary lung cancer were usually confirmed by pathological analysis, with the help of immunohistochemical staining of TTF-1, CDX2, CK7 and CK20, to differentiate the primary small bowel tumor from metastases of lung cancer." (PMID 22284720, 2012). "The ability of the top four candidates, CDKN2A EX2, CDX2, HOXA1 and OPCML (all p < 1 × 10-9), to individually identify lung cancer samples was next evaluated." (PMID 17967182, 2007). "In the present study, we investigated if there may be alternatives to the panel CDX2, CK7, CK20, and TTF-1 for differentiation between primary lung cancer and pulmonary metastases from the GI tract." (PMID 37349623, 2024). "Positive IHC staining for thyroid transcription factor 1 and cytokeratin-7 and negative staining for CK20 and CDX2 strongly correlate with GI metastases from lung cancer." (PMID 38957515, 2024). "This means that if a given lung cancer sample is positive for CDX2, the odds of it being non-primary are 333.3 times more than the odds of it being primary." (PMID 35027072, 2022). "Conversely, the PEAC phenotype did not express the “lung cancer marker” TTF-1 but was instead characterized by the “intestinal marker” CDX2." (PMID 26677401, 2015). "Immunohistochemical staining of the gastric tumor revealed adenocarcinoma that was positive for TTF-1 and caudal-related homeodomain protein 2 (CDX2) and negative for napsin A. In contrast, lung cancer tissue was weakly positive for TTF-1 and negative for napsin A and CDX2." (PMID 41635529, 2026).
lung carcinoma (continued). "Finally, CDX2 also stains other non-intestinal mucinous tumors, most notably carcinomas of lung, ovary and endometrium." (PMID 25299496, 2014). "Thus, the histological examination is the only way to identify metastatic tumors to the gastrointestinal tract, and immunostaining with TTF-1, CDX2, CK7 and CK20 is also helpful to distinguish primary gastrointestinal carcinoma from metastasis of lung carcinoma." (PMID 22741562, 2012). "Therefore, cdx2 should not be involved in the up-regulation of claudin-2 in lung cancer." (PMID 28608828, 2017). "CDX2, ALX4 and HOPX, three non-canonical HOX genes are hypermethylated in colorectal, pancreatic, gastric and lung cancers; however, the data on their methylation status in OC is less clear." (PMID 40002854, 2025). "The results of the lung tumor showed positive for TTF-1, Napsin-A, and CK7, while negative for CDX2 and CK20, ruling out the possibility of gastrointestinal origin and indicating primary lung cancer." (PMID 39465837, 2024).